LLGL2 (LLGL scribble cell polarity complex component 2)
Diseases named in the same sentence as LLGL2 in open-access papers:
LLGL2 is named in the same sentence as 24 diseases in open-access papers, as found by Europe PMC text mining. Sharing a sentence is not in itself a finding about the gene and the disease. The quoted sentences say what the papers report.
breast carcinoma (17 papers, 2018 to 2025). "Low LLGL2 mRNA expression was positively associated with longer DFS in all breast cancer patients analyzed in this study (P = 0.023)." (PMID 36192404, 2022). "The LLGL2 protein in the scribble complex was demonstrated to interact with the leucine transporter Slc7a5 to enhance the leucine uptake by ER + breast cancer cells, which promote cell proliferation and confer cancer cell drug resistance." (PMID 41274508, 2025). "LLGL2, a scaffold protein, is overexpressed in ER+ breast cancer and promotes ER+ breast cancer cell proliferation by regulating leucine uptake." (PMID 39973065, 2025). "Breast cancer cells upregulated LLGL2 expression to increase uptake of leucine under nutrient stress which is an essential amino acid for cell metabolism." (PMID 36593375, 2023). "LLGL2 expression is reduced in colorectal and breast cancers, and overexpression of zinc finger E box-binding homologous protein 1 (ZEB1) inhibits LLGL2 expression, leading to the loss of epithelial cell polarity and increased metastasis." (PMID 38136424, 2023). "Then, we investigated the association of prognosis with the combination of LLGL2 and SLC7A5 mRNA expression in ERα-positive breast cancer patients receiving adjuvant tamoxifen therapy." (PMID 36192404, 2022). "LLGL2 was also reported to function with SLC7A5 at cell junctions and membranes in ERα-positive breast cancer cells, and LLGL2 interacts with SLC7A5 to promote cell proliferation." (PMID 36192404, 2022). "The expression levels of LLGL2 protein in breast cancer tissue samples were examined by Immnohistochemistry (IHC)." (PMID 36192404, 2022). "We recently reported that LLGL2 overexpression promotes cell proliferation under nutrient stress conditions and regulates tamoxifen resistance in ER+ breast cancer cells." (PMID 35501367, 2022). "In this study, a total of 285 consecutive breast cancer tissue samples for which mRNA expression data were available were analyzed for LLGL2 protein expression." (PMID 36192404, 2022). "LLGL2 was reported to be involved in resistance to tamoxifen in ERα-positive breast cancer patients." (PMID 36192404, 2022). "One of Lgl mammalian homologues proteins, LLGL2 overexpression has been reported in ER+ breast cancer and promotes tumor proliferation through regulating leucine uptake." (PMID 34178676, 2021). "An emerging study demonstrates that LLGL2 involves in Hippo-YAP pathway which regulates bone metastasis in breast cancer." (PMID 30388870, 2018). "LLGL2 was reported to be involved in prognosis only in ERα-positive breast cancer patients." (PMID 36192404, 2022). "Similarly, the human gene encoding the Lgl homolog LLGL2/Hugl-2 contains E-box sequences and is directly bound and repressed by SNAIL in breast cancer cells." (PMID 34830224, 2021). "Notably, estrogen signaling induces LLGL2 expression, and LLGL2 was required for estrogen-mediated proliferation of breast cancer cells in low nutrients conditions (limited concentrations of glutamine and leucine)." (PMID 33953707, 2021). "Our study showed that co-expression of LLGL2 and SLC7A5 mRNA is a promising candidate biomarker in early breast cancer patients." (PMID 36192404, 2022). "Considering that SCRIB-P305L mutant interacts with LLGL2, SCRIB works as a scaffold of SLC7A5-SLC3A2 complex to direct the membrane localization of SLC3A2 in ER+ breast cancer cells." (PMID 35501367, 2022). "In this study, we assessed the effects of LLGL2/SLC7A5 co-expression in predicting prognosis and response to tamoxifen therapy in ERα-positive breast cancer patients with long-term follow up." (PMID 36192404, 2022). "In this study, we evaluated the prognostic value of co-expression of LLGL2 and SLC7A5 in primary breast cancer patients with long-term follow-up." (PMID 36192404, 2022).
breast carcinoma (continued). "LLGL2low/SLC7A5low showed longer survival compared with high LLGL2/SLC7A5 mRNA co-expression (LLGL2high/SLC7A5high) and a positive trend of longer survival compared with other combination groups in ERα-positive breast cancer patients." (PMID 36192404, 2022). "LLGL2 can suppress Snail-induced epithelial-mesenchymal transition (EMT), as a tumor suppressor preventing the dissemination of breast cancer." (PMID 34178676, 2021). "E-box sequences can be bound by other transcription factors, including ZEB-1, which has been shown to repress LLGL2, PATJ, and CRB3 in a breast cancer cell line." (PMID 34830224, 2021). "We and others have reported tumor-promoting roles of LLGL2 and SCRIB in breast cancer cells." (PMID 35501367, 2022). "This study aimed to assess the effects of LLGL2/SLC7A5 co-expression in predicting prognosis and response to tamoxifen therapy in ERα-positive breast cancer patients according to LLGL2/SLC7A5 mRNA and protein expression in long-term follow-up invasive breast cancer tissues." (PMID 36192404, 2022). "In human ER+ breast cancer, LLGL2 functions as a promoter of tumor growth, rather than a tumor repressor." (PMID 34178676, 2021). "In estrogen receptor (ER) positive breast cancers, LLGL2, but not LLGL1, is overexpressed, and its high expression correlates with poor patient survival." (PMID 33953707, 2021). "In breast cancer cells, NSUN6 can form a complex with the proteins LLGL2 and lncRNA Maya, which inactivates the kinase Hippo/MST1 through methylation of Hippo/MST1, resulting in promotion of tumor metastasis." (PMID 34630524, 2021). "Therefore, we hypothesized that both LLGL2 and SLC7A5 are required for the efficacy of tamoxifen treatment in ERα-positive breast cancer patients." (PMID 36192404, 2022). "Thus, our study showed that the co-expression of LLGL2 and SLC7A5 mRNA is a promising candidate biomarker and suggested that the LLGL2–SLC7A5 axis might be a therapeutic target in early breast cancer patients, especially in those receiving adjuvant tamoxifen therapy." (PMID 36192404, 2022).
colorectal cancer (4 papers, 2018 to 2025). A primary or metastatic malignant neoplasm that affects the colon or rectum. "Similarly, correlation-repressing genes RAB8A and LLGL2 associated with tight junction have previously been shown to be downregulated in colorectal cancer." (PMID 33384992, 2020).
epithelial ovarian cancer (2 papers, 2023 to 2025). "Low expression of LLGL2 was significantly associated with an advanced stage and a higher grade of ovarian cancer and a poorer survival of patients." (PMID 38136424, 2023). "LLGL2 was upregulated in ovarian cancer tissue, while low expression of LLGL2 was significantly associated with a more advanced stage and a higher grade of EOC and a poorer survival of patients, implying that LLGL2 may function as a tumor suppressor gene." (PMID 38136424, 2023). "In CSIOVDB, a transcriptomic microarray database of 3431 human ovarian cancers, low expression of LLGL2 was correlated with an advanced tumor stage and high grades of ovarian cancer (I vs. III, p < 0.0001; G1 vs. G3, p < 0.0001)." (PMID 38136424, 2023). "Our study found that LLGL2 was upregulated in ovarian cancer tissues, but its levels negatively correlated with malignant progression and the poor prognosis of ovarian cancer." (PMID 38136424, 2023). "LLGL2 is upregulated in ovarian cancer tissues but is negatively correlated with malignant progression and a poor prognosis of ovarian cancer." (PMID 38136424, 2023). "Our data demonstrated that overexpression of LLGL2 inhibited the ovarian cancer cell migration and invasion abilities in vivo and in vitro." (PMID 38136424, 2023). "To discover possible interacting molecules for LLGL2 in ovarian cancer, we obtained LLGL2-bound protein complexes by coimmunoprecipitation with a monoclonal antibody specific for LLGL2 in LLGL2-overexpressing ES-2 cells." (PMID 38136424, 2023). "LLGL2 was upregulated in ovarian cancer tissues, but its levels were negatively correlated with malignant progression and the poor prognosis of ovarian cancer." (PMID 38136424, 2023). "Collectively, these results suggested that LLGL2 was upregulated in ovarian cancer tissues but negatively correlated with malignant progression and a poor prognosis of ovarian cancer." (PMID 38136424, 2023). "This provides compelling evidence of a possible tumour suppressor role for LLGL2 in pre-metastatic epithelial ovarian cancer cells, corroborating the germline and somatic genomic data presented here to support it as a potentially novel HGSOC predisposition gene." (PMID 39794353, 2025). "To reveal how LLGL2 regulates ovarian cancer cell migration and invasion, we first investigated whether LLGL2 affected the EMT status." (PMID 38136424, 2023). "LLGL2 may play a role as a tumor suppressor gene in ovarian cancer." (PMID 38136424, 2023). "Thus, LLGL2 may function as a tumor suppressor gene in the context of ovarian cancer spreading." (PMID 38136424, 2023). "Therefore, LLGL2 may play a key role in the occurrence and development of ovarian cancer." (PMID 38136424, 2023). "Next, LLGL2 overexpression and knockdown experiments showed that LLGL2 inhibited the ovarian cancer cell migration and invasion abilities in vitro without affecting cell proliferation." (PMID 38136424, 2023). "Mechanistically, LLGL2 altered the intracellular localization and function of ACTN1 by interacting with ACTN1 and regulating cytoskeleton remodeling to inhibit the invasion and metastasis of ovarian cancer cells." (PMID 38136424, 2023). "Functional experiments that involved LLGL2 overexpression and knockdown showed that LLGL2 inhibited the migration and invasion abilities of ovarian cancer cells in vitro, without affecting their proliferation." (PMID 38136424, 2023). "However, the role of LLGL2 in ovarian cancer has not been described." (PMID 38136424, 2023).
hepatocellular carcinoma (2 papers, 2021 to 2024). A malignant tumor that arises from hepatocytes. "Nonetheless, the role of LLGL2 in hepatocellular carcinoma (HCC) is still unknown." (PMID 34178676, 2021). "In addition, LLGL2 can promote cell proliferation in hepatocellular carcinoma by activating phosphatidylinositol 3-kinase (PI3K)/Akt signaling and may serve as a therapeutic target in hepatocellular carcinoma." (PMID 38720397, 2024).
benign prostatic hyperplasia (1 paper, 2022). A non-cancerous nodular enlargement of the prostate gland. "In this study, to explore the new role of LLGL2 in the prostate, we examined the proliferative activity of a BPH-1 cell line, a well-established model for the human prostate biology of benign prostatic hyperplasia (BPH)." (PMID 36009528, 2022).
breast tumors (1 paper, 2024). "This revealed that both EPI (e.g. LLGL2, CLDN4, KRT7, ST14) and MES (e.g. SNAI1, VIM, AP1M1) genes positively correlated with PIEZO1 expression across all quintiles, whilst markers of luminal breast tumors (ESR1, FOXA1, PGR) negatively correlated in all instances." (PMID 38632473, 2024).
ductal adenocarcinoma (1 paper, 2024). "Similarly, aberrant localization or deletion of the second human Lgl homolog, LLGL2 (also known as HUGL2), is associated with gastric epithelial dysplasia and adenocarcinoma, and with pancreatic intraepithelial neoplasia and ductal adenocarcinoma." (PMID 38240353, 2024).
Hypertension (1 paper, 2015). The presence of chronic increased pressure in the systemic arterial system. "We have previously demonstrated that rs1671021 of LLGL2 is associated with ischemic stroke, although, to the best of our knowledge, variants of LLGL2 have not yet been associated with hypertension." (PMID 25813534, 2015).
liver cancer (1 paper, 2021). An epithelial or non-epithelial malignant neoplasm that arises from the liver. "The data demonstrated that LLGL2 expression is linked to tumor number (P<0.001), vascular infiltration (P<0.001), Edmondson-Steiner grade (P=0.013), Barcelona Clinic Liver Cancer (BCLC) Stage (P<0.001)." (PMID 34178676, 2021). "We established for the first time that LLGL2 mRNA and protein were remarkably overexpressed in the HCC tissues as well as liver cancer cell lines." (PMID 34178676, 2021).
melanoma (1 paper, 2022). A malignant, usually aggressive tumor composed of atypical, neoplastic melanocytes. "JQ1 was characterized by induction of inhibitory relationship linking regulators of inflammation (IFNG, IL17A, TGFB2), melanoma biological behavior (EGFR, WNT3A, TEADs, MRTFB), cell-cell interaction (CD44, CCN2), YAP pathway (LLGL2, NSUN6) and main transcriptional regulators (FOS, JUN, FOXM1)." (PMID 36397155, 2022).
pancreatic cancer (1 paper, 2024). "In humans, LLGL2 has been implicated in the progression of various cancers, including breast, hepatic, and pancreatic cancer." (PMID 38720397, 2024).
prostate carcinoma (1 paper, 2024). A carcinoma that arises from epithelial cells of the prostate gland. "Similarly, our results showed that autophagy induced by the knockdown of LLGL2 in prostate cancer cells was due to the loss of polarity when the LLGL2 was knockdown." (PMID 38720397, 2024). "However, the molecular mechanisms underlying the role of LLGL2 in prostate cancer (PCa) progression remain unknown." (PMID 38720397, 2024). "Therefore, LLGL2 may play a role in regulating of autophagy in prostate cancer cells." (PMID 38720397, 2024).
tumor (18 papers, 2008 to 2025). "Low LLGL2 mRNA levels were positively associated with larger tumor size (P = 0.047) and lymph node negativity (P = 0.031)." (PMID 36192404, 2022). "Overexpression of LLGL2 was linked to aggressive clinicopathological characteristics consisting of tumor number, vascular infiltration as well as advanced stage, and it was one of the independent risk indicators of OS and DFS in HCC." (PMID 34178676, 2021). "However, the functions and underlying mechanisms of LLGL2 in autophagy and tumor progression in PCa remain unknown." (PMID 38720397, 2024). "Nineteen genes (44%) demonstrated loss or promoter silencing of the wildtype allele in at least one tumour, with six genes (SLC12A4, LOXL2, ZCCHC4, LLGL2, MIPOL1, SCYL3) demonstrating this in multiple samples." (PMID 39794353, 2025). "LLGL2, as a scaffold protein for protein–protein and protein–RNA interactions, plays an important role in tumor progression." (PMID 38136424, 2023). "recently reported that LLGL2 promoted leucine uptake and conferred tumor growth and resistance to tamoxifen treatment by increasing the cell surface levels of SLC7A5 in Erα-positive breast cancer." (PMID 36192404, 2022). "Taken together, our study reveals that LLGL2 function as a tumor promoter by activating PI3K/AKT signaling through promoting Ca2+ influx in HCC." (PMID 34178676, 2021). "This study highlighted the tumor suppressor function of LLGL2 in CRC." (PMID 40619612, 2025). "LLGL2 was aberrantly expressed in various cancer tissues, suggesting that it may be involved in tumor progression." (PMID 38136424, 2023). "Indeed, LLGL2 was required for the surface localization of SLC7A5, suggesting that LLGL2 promotes tumor growth by upregulating nutrient transporters to enhance nutrient uptake within a nutrient-limited microenvironment." (PMID 33953707, 2021). "Our study identified that LLGL2 is a tumor promoter in HCC for the first time, which could potentially be utilized as a new biomarker and a therapeutic target for HCC." (PMID 34178676, 2021). "Smaller tumour size and negative association with TGFB1, CDH2 and LLGL2 strengthen the tumour suppressive role of KANK1." (PMID 31679074, 2020). "In the mouse tumour tissues, IHC analysis revealed that increased expression of SNAIL, VE‐cadherin and vimentin was observed in the HepG2‐LOXL2 cell‐xenograft tumours compared with the HepG2‐control cell‐xenograft tumours, whereas LLGL2 and E‐cadherin were expressed at lower levels." (PMID 30506621, 2019). "In addition, the results that the LOXL2 protein and mRNA levels were negatively correlated with LLGL2 expression in HCC tumour tissues and HCC cell lines were detected in this study." (PMID 30506621, 2019). "LLGL2 belongs to a group of genes that act as tumor suppressor genes." (PMID 18544165, 2008). "The roles of LLGL2 in tumorigenesis and subsequent tumor progression may be separated." (PMID 38136424, 2023). "Therefore, our data indicated that LLGL2 might functioned as a tumor promoter in HCC through activating PI3K/AKT signaling cascade by enhancing Ca2+ influx." (PMID 34178676, 2021). "Eight genes (CDH23, HARS2, LLGL2, LTBP1, MAP6D1, MIPOL1, SCYL3, ZNF418) showed some degree of promoter methylation in at least one tumour, but only MIPOL1 exhibited probable homozygous methylation in more than one sample." (PMID 39794353, 2025). "Thus, the roles of LLGL2 in tumorigenesis and subsequent tumor progression may be separated." (PMID 38136424, 2023). "LLGL2 was expressed in the cytoplasm and SLC7A5 in the plasma membrane, indicating co-expression in the same tumor cells." (PMID 36192404, 2022). "LLGL2 was up-regulated in HCC tissues, which was related with certain clinicopathological features including tumor number, vascular invasion as well as advanced stage." (PMID 34178676, 2021). "Hence a direct relationship between tumor suppression and SCRIB or LLGL2 proteins is controversial in mammals." (PMID 35501367, 2022).
tumor (continued). "According to this study, no role for Llgl2 as a tumor suppressor was observed, although the authors did not report evaluation of the mammary gland." (PMID 23110097, 2012). "Nevertheless, LLGL2 does not always serve as a typical tumor-suppressor gene in mammalian." (PMID 34178676, 2021).
cancer (15 papers, 2012 to 2025). A tumor composed of atypical neoplastic, often pleomorphic cells that invade other tissues. "As occurs in Drosophila, the mislocalization or dysfunction of LLGL1 and/or LLGL2 in cancer is also associated with altered aPKC localization or activity." (PMID 38240353, 2024). "Among them, LLGL2 expression is associated with cancer progression." (PMID 38720397, 2024). "Mislocalization of LLGL1 and/or LLGL2 is also observed in other human cancers, including lung adenocarcinoma and ovarian cancer." (PMID 38240353, 2024). "Collectively speaking, the increased levels of LLGL2, EGFR and decreased level in CDH1, recorded in the current study, promote EMT and cancer cell migration in BC." (PMID 33073304, 2021).
colon polyps (1 paper, 2023). "Among genes in this pathway, AS of LLGL2 (LLGL2_AP_43458) showed a significant increase in COAD with a history of colon polyps when compared to COAD patients without." (PMID 37810965, 2023).
LLGL2 also shares sentences with these, for which no sentence is quoted: ovarian cancer (2 papers); adenocarcinoma (1); adenomyosis (1); colon cancers (1); gastric cancer (1); invasive breast carcinoma (1); ischemic stroke (1); lung adenocarcinoma (1); lymph node metastasis (1).